DNMT3B (DNA methyltransferase 3 beta)
Diseases named in the same sentence as DNMT3B in open-access papers (continued):
Sharing a sentence is not in itself a finding about the gene and the disease.
breast carcinoma (continued). "We used human breast cancer cell line MDA-MB-453 in our study, because according to the literature it is a hypemethylator cell line representing high level of DNMTs activity and overexpression of DNMT3B along with silencing of multiple methylation sensitive genes." (PMID 28979331, 2017). "We also observed that enforced expression of regulatory miRs results in reduced DNMT3b mRNA levels in hypermethylator breast cancer cell lines, and that down-regulation of regulatory miRs results in increased DNMT3b mRNA levels in non-hypermethylator breast cancer cell lines." (PMID 22664488, 2012). "However, the molecular mechanism that governs the overexpression of DNMT3b among hypermethylator breast cancer cell lines has not been investigated." (PMID 22664488, 2012). "However, we found that knockdown of DNMT1, but not DNMT3a and DNMT3b, resulted in restoration of FOXO3a expression, indicating that the downregulation of FOXO3a is associated with DNMT1-mediated hypermethylation of its promoter in breast cancer." (PMID 31296961, 2020). "Moreover, an increase of de novo DNA methylation activity of DNMT3B following its interaction with NEDDylated CUL4A (CUL4A-NEDD8) could be involved in local DNA hypermethylation and was reported in tissues (e.g., breast cancer (BC) and hepatoma) overexpressing CUL4A." (PMID 29449903, 2018). "Finally, a significant anti-correlation between the expression levels of GATA3 and DNMT3B, initially observed in the TCGA–BRCA dataset, was confirmed in our validation cohort, suggesting that GATA3 may indeed be down-regulated by the aberrant activation of DNMT3B in breast cancer." (PMID 40585280, 2025). "These analyses revealed five genes, DNMT3B, EXO1, MCM10, CENPF and CENPE, that are normally not expressed in healthy breast tissue but become frequently activated in breast cancers." (PMID 37592220, 2023). "DNMT3B expression in HER2 positive and triple-negative breast cancer were higher than that in luminal breast cancer." (PMID 35812757, 2022). "In contrast, knockdown of miR-148b, miR-26b, or miR-29c in non-hypermethylated breast cancer cell lines (MDA-MB-468, MDA-MB-415, and BT20) showed increased DNMT3b mRNA levels." (PMID 33050637, 2020). "Further analysis revealed that more than half of DNMT3B/ALYREF-miRNA pairs showed positive expression correlation (51.3% for DNMT3B and 55.0% for ALYREF) in breast cancer, but only 10.1 and 25.0% pairs presented negative expression relationship for DNMT3B and ALYREF, respectively." (PMID 35812757, 2022). "Interestingly, one study reported that DNMT3B expression was elevated in breast tumor subjects, but DNMT3A expression was not changed in breast cancer specimens in comparison to normal tissues, suggesting that deep exploration is necessary to determine the role of DNMT3A in breast cancer." (PMID 35620052, 2022).
lung carcinoma (81 papers, 2007 to 2025). "Our study found that subjects with lower miR-29b expression or higher DNMT3B mRNA expression had a significantly increased risk of lung cancer." (PMID 35627221, 2022). "Smokers with both lower miR-29b and higher DNMT3B mRNA expression levels (OR 5.12, 95% CI 2.64–9.91), and smokers with both higher miR-29b and higher DNMT3B mRNA expression levels (OR 6.88, 95% CI 3.27–14.46) had an evident risk of lung cancer." (PMID 35627221, 2022). "Even though non-smokers are not exposed to cigarettes, those with lower miR-29b expression and higher DNMT3B mRNA expression risk developing lung cancer." (PMID 35627221, 2022). "A borderline significant interaction between cumulative smoking dose and DNMT3B − 149 genotypes on lung cancer risk was still maintained (p = 0.07)." (PMID 34587932, 2021). "Our previous study further revealed that the DNMT3B − 149 TT genotype can increase the lung cancer risk caused by smoking." (PMID 34587932, 2021). "Subsequently, we respectively analyzed the joint effects of smoking status with DNMT3B − 149 genotypes and DNA damage level on lung cancer risk." (PMID 34587932, 2021). "The present study found that the combined effect between smoking and DNMT3B − 149 genotypes on lung cancer risk is significant, although the interaction only reached marginal statistical significance." (PMID 34587932, 2021). "Last, we analyzed the joint effects of green tea consumption, DNMT3B − 149 genotypes and DNA damage level on lung cancer risk." (PMID 34587932, 2021). "Compared with nonsmokers carrying the DNMT3B − 149 CT genotype, smokers carrying the DNMT3B − 149 TT genotype had a higher lung cancer risk (OR: 2.83, 95% CI: 1.62–4.93)." (PMID 34587932, 2021). "A borderline significant interaction between smoking status and DNMT3B − 149 genotypes on lung cancer risk was observed (p = 0.06)." (PMID 34587932, 2021). "We designed a case-control study to evaluate the combined effects of smoking, green tea consumption, DNMT3B − 149 polymorphism, and DNA damage on lung cancer occurrence." (PMID 34587932, 2021). "Aberrant DNA methylation caused by the DNMT3B complex in lung cancer is well established and proposed as a possible therapeutic target." (PMID 33233545, 2020). "The present study investigated the association between two DNMT3B polymorphisms, −149C>T and −2437T>A, and lung cancer risk." (PMID 27876061, 2016). "Currently, other DNMT3B polymorphisms, such as −579G>T and −283T>C, are investigated to ascertain their influences on lung cancer." (PMID 27876061, 2016). "Nevertheless, our findings are of great value to provide a novel insight into effects of DNMT3B polymorphisms on risk of lung cancer among Chinese population." (PMID 27876061, 2016). "Herein, we conducted this case-control study recruiting a total of 1286 Chinese participants (684 cases and 602 controls), to explore the effects of DNMT3B −149C>T polymorphism on the susceptibility of lung cancer in Chinese population." (PMID 27876061, 2016). "DNMT3B −2437T>A is a novel polymorphism, and its influence on the risk of lung cancer in Chinese was investigated in this study." (PMID 27876061, 2016). "For example, there are associations between DNMT3B genotype, breast cancer susceptibility, lung cancer susceptibility and prostate cancer progression." (PMID 24098518, 2013). "miR-29 family members (miR-29a, -29b, and -29c), which are inversely expressed related to DNM3a and DNMT3b, in lung cancer tissue are directly associated with 3′UTR mRNA region of DNMT3a and DNMT3b." (PMID 21860617, 2012). "In addition, age and gender were associated with miR-29b and DNMT3B mRNA expression in our lung cancer subjects." (PMID 35627221, 2022). "Similarly, green tea nondrinkers with higher DNMT3B mRNA expression had a 1.42-fold (95% CI 0.94–2.14) higher risk of lung cancer than green tea drinkers with lower DNMT3B mRNA expression." (PMID 35627221, 2022).
lung carcinoma (continued). "Further, our previous study observed that the DNMT3B-149 TT genotype with higher promoter activity could increase the lung cancer risk elicited by smoking." (PMID 35627221, 2022). "Our study suggested that the DNMT3B − 149 TT genotype, which has higher promoter activity, can increase the lung cancer risk elicited by smoking, and DNA damage may further promote smoking related lung cancer development." (PMID 34587932, 2021). "Taken together, the DNMT3B − 149 TT genotype, which has higher promoter activity, could increase the lung cancer risk elicited by cigarette smoking, and greater DNA damage might further promote smoking related lung cancer development." (PMID 34587932, 2021). "DNMT3B polymorphisms are associated with the susceptibility of lung cancer." (PMID 27876061, 2016). "In addition, we identified a novel DNMT3B polymorphism, −2437T>A, and also explored its relationship with lung cancer risk." (PMID 27876061, 2016). "Furthermore, we investigated influence from haplotypes of the two DNMT3B polymorphisms on the risk of lung cancer, aiming to provide novel insights into mechanisms on lung cancer development regulated by DNMT3B gene." (PMID 27876061, 2016). "DNMT3B −149C>T polymorphism is known to enhance the gene’s promoter activity, and a previous study has demonstrated that T-allele carrier genotypes, especially CT genotype, are significantly related to increased risk of lung cancer." (PMID 27876061, 2016). "Rs2424913 has previously been implicated in altered DNMT3B promoter activity and lung cancer risk." (PMID 24098518, 2013). "For instance, lncRNA HOTAIR has been shown to associate with DNMT1, DNMT3A, and DNMT3B, which are concentrated in the promoter regions of genes associated with tumor metastasis, resulting in hypermethylation of these genes and promoting the metastatic potential of lung cancer cells." (PMID 41394878, 2025). "Furthermore, we observed that smokers with lower miR-29b and higher DNMT3B mRNA expression levels had a more pronounced lung cancer risk than other combinations of smoking status with miR-29b and DNMT3B mRNA expression, except for smokers with higher miR-29b and higher DNMT3B mRNA expression levels." (PMID 35627221, 2022). "Thus, misclassification of exposure may have influenced the effect of specific variables on miR-29b expression, DNMT3B mRNA expression, and lung cancer risk." (PMID 35627221, 2022). "However, the present study could not detect a significant combined effect between green tea consumption and DNMT3B − 149 genotypes on lung cancer risk." (PMID 34587932, 2021). "On the whole, this study suggested that the DNMT3B − 149 TT genotype, which has higher promoter activity, could increase the lung cancer risk elicited by cigarette smoking, and greater DNA damage might further promote smoking related lung cancer development." (PMID 34587932, 2021). "In addition, effect of DNMT3B −149C>T polymorphism on lung cancer was also explored." (PMID 27876061, 2016). "It is hypothesized that haplotypes of DNMT3B polymorphisms may regulate the susceptibility to lung cancer, and among the three DNMT3B polymorphisms (−149C>T, −579G>T, and −283T>C), the haplotype −283T/−579G is reported to have a decreased effect on the risk of lung adenocarcinoma." (PMID 27876061, 2016). "In contrast, HOPX knockdown partially recovered the malignant phenotypes of lung cancer cells treated with SGI-1027 or si-DNMT3B." (PMID 41660264, 2025). "Nevertheless, the functional mechanisms through which DNMT3B promotes the malignant progression of lung cancer remain incompletely understood and require further investigation." (PMID 41660264, 2025). "In this study, we demonstrated that DNMT3B promoted proliferation, migration, and invasion of lung cancer cells in vitro and facilitated tumor growth in vivo in xenograft models." (PMID 41660264, 2025).
lung carcinoma (continued). "Furthermore, the results of various meta-analyses have demonstrated that the polymorphism rs1569686 of the DNMT3B gene could play a protective role against lung cancer and colorectal cancer in Asians and in the Azerbaijani population and against gastric carcinogenesis." (PMID 38504781, 2024). "In this study, we found that 1,2-NQ, an environmental electrophile, alters epigenetic regulation by modifying DNMT3B, leading to aberrant cell growth in a lung cancer cell line." (PMID 39519144, 2024). "Metformin dose-dependently downregulated expression of DNMT1 and DNMT3a at the post-transcriptional level and expression of DNMT3b at the transcriptional level in A549 lung cancer cells." (PMID 36959680, 2023). "Altered expression levels of DNMT1, DNMT3a, and DNMT3b proteins have been found in patients with lung cancers, especially in smokers, and are correlated with hypermethylation of tumor suppressor genes." (PMID 36959680, 2023). "The same working group also revealed that in lung cancer patients, lower levels of FOXO3 and higher levels of DNMT3B were correlated with a poor prognosis for lung cancer." (PMID 38132107, 2023). "In the present study, lung cancer patients had significantly lower miR-29b expression and significantly higher DNMT3B mRNA expression than did healthy controls." (PMID 35627221, 2022). "Results revealed that lung cancer patients had lower miR-29b expression (57.2 vs. 81.6; p = 0.02) and higher DNMT3B mRNA expression (37.2 vs. 25.8; p < 0.001) than healthy controls." (PMID 35627221, 2022). "A total of 132 lung cancer patients and 132 healthy controls were recruited to measure miR-29b and DNMT3B mRNA expression in whole blood." (PMID 35627221, 2022). "The interaction between green tea consumption and DNMT3B mRNA expression in lung cancer development was significant (p < 0.001)." (PMID 35627221, 2022). "A significant interaction between smoking status and miR-29b and DNMT3B mRNA expression levels in lung cancer development remained (p < 0.001)." (PMID 35627221, 2022). "The combined effects of green tea consumption with miR-29b and DNMT3B mRNA expression on lung cancer development were also evaluated." (PMID 35627221, 2022). "The joint effect of green tea consumption with miR-29b and DNMT3B mRNA expression was also evident in the development of lung cancer." (PMID 35627221, 2022). "When effects of smoking status, miR-29b, and DNMT3B mRNA expression were further assessed simultaneously, we also found significant interaction between these three factors in lung cancer development." (PMID 35627221, 2022). "Currently, our study highlights the significant interaction of smoking with miR-29b expression, and that of smoking with DNMT3B mRNA expression in lung cancer development." (PMID 35627221, 2022). "Interaction of green tea consumption with miR-29b expression and DNMT3B mRNA expression in lung cancer was also significant." (PMID 35627221, 2022). "A significant interaction between smoking status and DNMT3B mRNA expression in lung cancer development was also observed (p = 0.001)." (PMID 35627221, 2022). "The interactions of cigarette smoking with miR-29b and DNMT3B mRNA expression levels were both significant in the development of lung cancer." (PMID 35627221, 2022). "We evaluated the joint effects of miR-29b and DNMT3B mRNA expression in the development of lung cancer." (PMID 35627221, 2022). "Subsequently, we evaluated the joint effects of smoking status with miR-29b and DNMT3B mRNA expression in the development of lung cancer." (PMID 35627221, 2022). "The current case–control study compared the differences in whole blood miR-29b and DNMT3B mRNA expression between lung cancer patients and healthy controls." (PMID 35627221, 2022). "Herein, we designed a case–control study to evaluate the joint effects of smoking and green tea consumption, with miR-29b and DNMT3B mRNA expression, in lung cancer development." (PMID 35627221, 2022).
lung carcinoma (continued). "The expression of DNMT3A and DNMT3B was high in lung cancer, and the expression of the miR-29 family was negatively correlated with them." (PMID 35478963, 2022). "It has been observed that miR-29b can directly target DNMT3B, and miR-29b expression is inversely correlated to DNMT3B expression in lung cancer tissues." (PMID 35627221, 2022). "In particular, the relationship between the analyzed variables, miR-29b expression, and DNMT3B mRNA expression, showed different directions in the respective groups of lung cancer cases and healthy controls." (PMID 35627221, 2022). "Contrarily, lung cancer patients had significantly higher DNMT3B mRNA expression than healthy controls (37.2 vs. 25.8, p < 0.001)." (PMID 35627221, 2022). "We further tested the interactions of smoking, green tea consumption, DNMT3B − 149 genotypes, and individual DNA damage level in the occurrence of lung cancer." (PMID 34587932, 2021). "Researchers selected also the protein DNA (cytosine-5)-methyltransferase 3β (DNMT3B) complex as significantly upregulated in BALF-EVs from lung cancer patients." (PMID 33915715, 2021). "As in our previous studies, independent effects of smoking, green tea consumption, and DNMT3B − 149 genotypes on the development of lung cancer were observed." (PMID 34587932, 2021). "As expected, the independent effect of DNMT3B − 149 genotypes on the development of lung cancer in Taiwanese cases was observed." (PMID 34587932, 2021). "For instance, c‐Myc recruits DNMT3b to the promoter region of RASSF1A, which causes DNA hypermethylation and reduces RASSF1A expression in lung cancer cells." (PMID 34057794, 2021). "Various solid cancers overexpress DNMT3B transcripts including lung cancer, and DNMT3B is considered a potential therapeutic target." (PMID 33233545, 2020). "The fungus dramatically increased GA up to 44.8 fold in the post-fermentation oolong tea extract (PFOTE), resulting in enhanced demethylation effects and a significant reduction in the nuclear abundances of DNMT1, DNMT3A, and DNMT3B in lung cancer cell lines." (PMID 29416619, 2018). "As a critical enzyme participating in de novo DNA methylation, DNMT3B is thought to silence tumor suppress genes by methylating cytosine sites in gene promoters during the early stages of lung cancer development." (PMID 26942697, 2016). "Knockdown of DNMT3B enhanced the radiosensitivity of lung cancer A549 cells to both γ-irradiation and carbon-ion beam irradiation." (PMID 26667181, 2015). "DNMT3b has been reported to participate in carcinogenesis of several cancer types including esophageal, gastric and lung cancer, but the role of DNMT3b in OSCC requires further investigation." (PMID 24625449, 2014). "DNA methylation of the RASSF1A promoter involves PRC2 and DNMT3B DNA-methyl transferase in lung carcinoma cell lines that have high HOX3B expression." (PMID 23990798, 2013). "For example, Sengupta and his colleagues have shown that miR-29c is down-regulated in nasopharyngeal carcinomas, while Fabbri and his colleagues discovered that the miR-29 family, including miR-29c, targets DNMT3A and DNMT3B in lung cancer tissues and cells." (PMID 23936390, 2013). "The reduced expression of the miR-29 family induced overexpression of DNMT3A and DNMT3B, resulting in aberrant DNA methylation in lung cancer." (PMID 23056009, 2012). "Loss of expression of members of miR-29 family and overexpression of DNMT3b has been shown in lung cancer and acute myeloid leukemia." (PMID 22664488, 2012). "A recent study has revealed that miR-29 family (miR-29a, miR-29b, and miR-29c) target the de novo DNA methyltransferases DNMT3A and DNMT3B and expression levels of miR-29 family were suppressed in lung cancer." (PMID 23056009, 2012). "The miR-29 family (miR-29a, miR-29b, miR-29c) directly targets DNMT3a and DNMT3b in lung cancer and acute myeloid leukemia." (PMID 22664488, 2012).